BDNF (brain derived neurotrophic factor)
Diseases named in the same sentence as BDNF in open-access papers (continued):
Sharing a sentence is not in itself a finding about the gene and the disease.
depression (continued). "Meanwhile, chronic administration of antidepressants increases the expression, phosphorylation, and function of CREB, and its downstream target gene BDNF in the limbic brain regions related to depression." (PMID 30487761, 2018). "Accumulating evidence shows that expression of brain-derived neurotrophic factor (BDNF) is involved in the pathophysiological mechanisms of depression and PSD." (PMID 30061860, 2018). "BDNF level decrease induced by stress results in aberrant neurogenesis and subsequent depression, whereas its increase follows anti- depressant treatment." (PMID 29506545, 2018). "Phillips (2017) has suggested that neuroplasticity that takes place in major depressive disorder (MDD) is related to BDNF levels." (PMID 29899693, 2018). "Reduction of hippocampal BDNF attenuates the effect of antidepressants, and infusion of BDNF into the hippocampus reverses depression-like behavior in rodents." (PMID 29867393, 2018). "Since up to 50% of AD patients suffer from depression, making this disorder one of the most frequent comorbidities in such patients, it would be critical to discriminate depression-related from dementia-related BDNF changes." (PMID 29330839, 2018). "Since CREB and BDNF both play an important role in neuronal plasticity, both molecules are often regarded as key factors in the pathophysiology of depression and as targets of antidepressant drugs." (PMID 30294251, 2018). "Knowing that, in a rat model of depression, increases in BDNF in the VTA-NAc induced pro-depressive-like effects, the use of partial antagonists as a treatment for diseases related to nervous system dysregulations has been considered." (PMID 29961124, 2018). "An epigenetic study of anxiety/depression in older women found higher BDNF DNA methylation in subjects with anxiety/depression than in controls, and this difference was more pronounced in BDNF Val66Met heterozygotes than in Val homozygotes." (PMID 29867348, 2018). "BDNF has been introduced to treatment-resistant depression and it has been identified as a therapeutic target for depression." (PMID 29986408, 2018). "Previous studies have shown that brain-derived neurotrophic factor precursor (proBDNF) is involved in the development of depression." (PMID 30740068, 2018). "Bupleurum-saikoside, the main active ingredient of Bupleuri Radix, improved depression by regulating the monoamine neurotransmitters and BDNF in the brain." (PMID 29991955, 2018). "A three-way interaction between brain-derived neurotrophic factor (BDNF) genotype, 5HTTLPR, and maltreatment history was related to depression in children, and this relation was moderated by social support." (PMID 29427067, 2018). "More studies should be done on NMDA and BDNF in the future to develop a treatment for depression that can effectively and efficiently control the depressive episode and provide baseline mood maintenance in the long-term." (PMID 30034974, 2018). "Chronic unpredictable stress is associated with depression and with learning and memory impairments via the cAMP/protein kinase A (PKA)/CREB/BDNF signal cascade." (PMID 30065945, 2018). "BDNF is a downstream effector of CREB and has been shown to mitigate and repair depression-associated neuronal injury." (PMID 29941796, 2018). "Adding even further to the difficulty of studying BPD-specific effects, BDNF methylation was also found associated with a broad range of psychiatric symptoms and disorders other than BPD, such as bipolar disorder, depression, schizophrenia, and suicidality." (PMID 30134995, 2018). "Several lines of evidence indicate that cerebral BDNF is an effector of and a therapeutic target for depression." (PMID 29330839, 2018). "The first would involve excluding from AD cohorts those patients who suffer from clinical depression or by assessing its influence on BDNF levels." (PMID 29330839, 2018).
depression (continued). "The Val66Met polymorphism affects a particular step of proBDNF processing that is sufficient to impair the formation of enough levels of mature BDNF and trigger familiar depression." (PMID 30428894, 2018). "We demonstrated that a single administration of HBK-15—a triple 5-HT1A, 5-HT7, and 5-HT3 receptor antagonist—reversed depression-like behavior and regulated decreased BDNF level in the hippocampus in mouse with corticosterone-induced model of depression." (PMID 28550529, 2018). "The study also reported that a rise in BDNF after ketamine infusion was correlated with a decrease in the Montgomery-Asberg Depression Rating Scale score." (PMID 30034974, 2018). "Strong evidence has revealed a reduction in mRNA and protein levels of BDNF in patients and rat model of depression relative to those of controls and recovery after antidepressant treatment." (PMID 30410555, 2018). "This study showed that administration of HSR significantly reduced the depression-like behavior by activating the CREB/BDNF signaling pathway in a mouse model of depression induced by restraint stress." (PMID 30581865, 2018). "It is well established that brain-derived neurotrophic factor (BDNF) signaling pathway plays a key role in the pathophysiology of major depressive disorder (MDD) and in therapeutic mechanisms of antidepressants." (PMID 29725086, 2018). "Epidemiological and review studies have reported a relation between depression and decreases in cognitive function, brain volume, and expression of brain-derived neurotrophic factor (BDNF)." (PMID 30305151, 2018). "Epigenetic mechanisms, including DNA methylation, histone modifications, and non-coding RNAs, are considered to be very important for BDNF expression regulation and involved in the pathogenesis of depression." (PMID 29636708, 2018). "The BDNF level isreduced in the blood plasma of patients with depression; after treatment withantidepressants, the BDNF level returns to normal values." (PMID 30397531, 2018). "Increased expression of BDNF in the hippocampus and cortex produces an antidepressant-like effect in both corticosterone and chronic unpredictable mild stress-induced depression-like animal models." (PMID 29419799, 2018). "To further confirm the upregulation of proBDNF in depression and anxiety disorders, we examined the expression of proBDNF and mature BDNF in the hippocampus of these two rat models established in the present study." (PMID 30740068, 2018). "Previous animal study showed that BDNF knockdown in the hippocampal subregion produced depression-like behaviors in rats." (PMID 29357818, 2018). "There is strong evidence supporting the existence of a relationship between depression and BDNF expression, but exactly how antidepressant medications and resveratrol are able to manipulate this relationship is still being researched." (PMID 30200269, 2018). "We found that a single administration of HBK-15—a triple 5-HT1A, 5-HT7, and 5-HT3 receptor antagonist—reversed depression-like behavior and regulated decreased BDNF level in the hippocampus in mice with corticosterone-induced depression model." (PMID 28550529, 2018). "It is well known that BDNF is a biomarker for depression, although this correlation remains to be shown in MS patients, whose immune cells secrete lower than normal BDNF." (PMID 29872382, 2018). "In the decades that have passed, since the correlation between BDNF levels and the development of depression were identified, there has been considerable progress in understanding the roles of BDNF and its contributions to the pathogenesis of depression." (PMID 29636708, 2018). "With regard to the peripheral consequences of depression, a reduction in serum and plasma BDNF has repeatedly been reported, even though its functional role is unclear." (PMID 29330839, 2018).
depression (continued). "Except for these findings, the present study further provided new findings between microglial M1 and M2-phenotypes and pro- and mature BDNF function in the LPS-induced depression." (PMID 30248907, 2018). "The increase in plasma BDNF concentration and the associated decrease in depressive symptoms and improvements in sleep quality observed in the exercise group adds further support to the interplay between depression, sleep quality, and BDNF that may underlie the onset and recovery of MDD." (PMID 29559928, 2018). "The CUMS procedures elevated the expression level of HDAC2 and induced the downregulation of acH3K9 protein and BDNF mRNA, and ultimately contributed to depressive disorder." (PMID 29636708, 2018). "Depression and chronic stress disrupt BDNF signaling, including reductions in the ERKs, PI3K/Akt, and CREB pathways, which are important mediators of the signal transduction pathways." (PMID 30038568, 2018). "After antidepressant treatment, the cAMP/PKA pathway was activated and the level of BDNF was negatively correlated with the depression scale scores of patients." (PMID 28352129, 2017). "For each BDNF genotype, the hippocampal volumes were significantly lower in neuropsychiatric patients (including depression) than in healthy controls." (PMID 29019461, 2017). "Decreased BDNF signaling has been thoroughly studied in the context of depression, and numerous transgenic mouse models of impaired BDNF function have been generated." (PMID 29232822, 2017). "n-3 PUFAs: Interestingly, the prolonged consumption of an n-3 PUFA deficient diet impaired dopamine signaling and decreased BDNF levels in the striatum of rodents, suggesting an increased vulnerability to depression-like behaviors." (PMID 28304335, 2017). "Expression of BDNF is influenced by many conditions including stress, cigarette smoking, alcoholic consumption, and depression." (PMID 29164087, 2017). "Among them, brain-derived neurotrophic factor (BDNF) has key roles in the neurobiological mechanisms related to major depression." (PMID 29348904, 2017). "For example, ECS-induced reductions in depression-like behavior were found to be accompanied by normalization of BDNF and Neuropeptide Y expression in brain areas relevant to depression." (PMID 28910337, 2017). "In comparison, mice with chronic stress-induced depression exhibit decreased hippocampal BDNF expression and reduced number of entries into the center area of the open field (OF) test." (PMID 28872625, 2017). "Nevertheless, key mechanisms related to depression such as hippocampal cell proliferation and brain-derived neurotrophic factor (BDNF) expression levels were shown to differ between the two strains, potentially indicating important interstrain differences." (PMID 28771575, 2017). "The BDNF level of patients with depression has been found to be significantly reduced in several studies." (PMID 28706741, 2017). "Although these reductions were not significantly different from controls, the reduction of brain BDNF levels are partly responsible for ethanol-induced depression." (PMID 28837087, 2017). "Low BDNF levels are found in patients with neurodegenerative diseases, including Alzheimer’s disease, and major depression." (PMID 29312105, 2017). "Recent developments linking BDNF to a wide array of pathogenesis in depression and its treatment outcomes are highlighted." (PMID 28415673, 2017). "Stress reduces the expression and function of BDNF in brain structures related to the pathogenesis of depression." (PMID 28446154, 2017). "On the other hand, several animal models of depression have also shown a reduced expression of BDNF in brain regions and produce an antidepressant-like behavior." (PMID 28118829, 2017). "BDNF abnormalities also contribute to dysfunction of astrocytes and microglia in depression circuits." (PMID 28928987, 2017).
depression (continued). "They found no additional increase of BDNF in the exercise plus medication group relative to the medication-only group, suggesting a plateau effect of antidepressant drugs on BDNF levels in persons with depression." (PMID 28928987, 2017). "Significant interactions between 5-HTTPR and BDNF genes and stressful life events have been reported in patients with depression." (PMID 28225778, 2017). "Levels of BDNF in the PFC of rats with depression-like phenotype were significantly lower than those of rats without depression-like phenotype and sham-operated rats (P < 0.05)." (PMID 28600519, 2017). "Recently, growing evidence has suggested that BDNF is also involved in neurogenesis, and newborn neurons contribute to the recovery process of depression-like behaviors." (PMID 29099059, 2017). "Our previous work indicated that combination of serum levels of multiple proteins in tissue plasminogen activator (tPA)-brain-derived neurotrophic factor (BDNF) pathway improved accuracy of diagnosis of major depressive disorder (MDD)." (PMID 28761093, 2017). "Although few studies appointing to a relationship among BDNF levels, depression and sleep, this issue is still unclear." (PMID 29299044, 2017). "Dunham and colleagues reported a reduction of pro-BDNF in all layers of the right hippocampus in persons with depression." (PMID 28928987, 2017). "All the evidence pointing to the fact that treatment for depression shows an improvement in BDNF expression, it is still unclear how discontinuation of antidepressant medication would affect these levels." (PMID 29299044, 2017). "In summary, our meta-analyses of 20 studies related to depression provided evidence that peripheral BDNF levels are increased during the course of antidepressant drug treatment (SSRIs and SNRIs)." (PMID 28241064, 2017). "Altogether, the data presented here suggests that moderate PA—a target that is practical, well tolerated, and likely to optimize exercise adherence—optimizes BDNF and plasticity, particularly in persons with depression." (PMID 28928987, 2017). "Alterations of brain BDNF levels in the pathophysiology of depression and the effects of antidepressants depend on brain areas." (PMID 28837087, 2017). "As proBDNF binding to p75NTR has opposing biological consequences to BDNF, it is essential to differentiate proBDNF from BDNF in depression." (PMID 28375203, 2017). "We decided to use the lower dosage because it was previously used in mice and had been shown to improve depression-like phenotype, increase BDNF levels and reduce corticosterone levels in other mouse experiments." (PMID 29073219, 2017). "BDNF has been shown to participate in the pathogenesis of migraine comorbidities, such as epilepsy and depression, and a strong relationship between migraine and depression in pathogenetic mechanisms has been confirmed by previous documents." (PMID 27875242, 2017). "Other outcome measures were aerobic fitness, depression scores, quality-of-life and life-satisfaction scores, and markers of brain plasticity (brain-derived neurotrophic factor – BDNF)." (PMID 29276545, 2017). "Additionally, lurasidone has been demonstrated to exert antidepressant properties through a direct modulation of BDNF in prefrontal cortex of animal models of depressive states, thus suggesting a crucial impact of this drug on pathophysiologic neuroplastic mechanisms underlying depression." (PMID 28085108, 2017). "A greater knowledge of the interrelationship between BDNF, depression, therapeutic mechanisms of action, and neuroplasticity is important as it necessarily precedes the derivation and deployment of more efficacious treatments." (PMID 28928987, 2017). "The relationship between circulating BDNF and brain function has been demonstrated in populations with depression and in aging populations." (PMID 29056915, 2017).
depression (continued). "The hippocampus is a site of life long neurogenesis, with decreased BDNF expression and diminished neuro/synaptogenesis accompanying episodes of major depression." (PMID 28713269, 2017). "The fundamental involvement of BDNF in psychiatric disorders has been confirmed by a meta-analysis which correlated decreased serum BDNF to major depressive disorders." (PMID 29403399, 2017). "Brain derived neurotrophic factor (BDNF) is one of the most important regulatory proteins in the pathophysiology of major depressive disorder (MDD)." (PMID 28241064, 2017). "In vivo, the treatment for 5 days (12 and 24 mg/kg, per os) with SA or fluoxetine prevented the development of the depression-like behavior and of the downregulation of BDNF protein levels in the hippocampus induced by a single injection of LPS." (PMID 29464125, 2017). "Previous work reported that ICA treatment elevated the mRNA and protein expression of BDNF and TrkB in the hippocampi of AD and depression model rats." (PMID 29057264, 2017). "Some authors argue that most of the cases show that impaired sleep quality increases the stress and, consequently, the vulnerability to depressive disorders, suggesting that there is a relationship between sleep, depression and BDNF levels." (PMID 29299044, 2017). "Other studies in animals indicate that serum BDNF levels are predictive for the vulnerability to develop epilepsy after an insult, and for the development of comorbidities such as depression and cognitive deficits." (PMID 35098038, 2017). "Hippocampal and peripheral BDNF has an anxiolytic-like behavioral effect in animal models of anxiety and depression." (PMID 28872625, 2017). "A single systemic administration of 7,8-DHF promoted a rapid antidepressant effect in inflammation model of depression, implicating BDNF-TrkB signal pathway in the PFC, DG, and CA3 in the antidepressant action of TrkB agonist." (PMID 27844095, 2017). "CREB (cAMP response-element binding protein)-BDNF (brain derived neurotrophic factor) pathway is a well known pathway in depression." (PMID 28938610, 2017). "This work establishes BDNFVal66Met genotype as a regulator of behavioral despair, and identifies new biological targets of BDNF genetic variation relevant to stress-inducible disorders such as depression." (PMID 28926000, 2017). "Given the established use of social isolation to model the symptoms of schizophrenia and depression, future research should focus on exploring the mechanistic links between chronic social isolation, BDNF expression and the elicited behavioral alterations." (PMID 28620285, 2017). "BDNF appears to be involved in the genesis of many depression cases; several depressive patients present reduced BDNF levels." (PMID 28056040, 2017). "An inverse correlation was observed between serum BDNF levels and depression severity in one clinical trial." (PMID 28713269, 2017). "In an earlier study, we also found increased BDNF in the hippocampi of rats in an unpredictable chronic mild stress (UCMS) model of depression compared with control rats." (PMID 29348904, 2017). "We reported that lipopolysaccharide-induced inflammation and social defeat stress increased BDNF levels in the NAc, resulting in depression-like phenotype in mice." (PMID 28769056, 2017). "Recent studies have shown that human BDNF level decreases in patients with schizophrenia, bipolar disorder, dementia and depression and antidepressants can increase its level." (PMID 29552054, 2017). "BDNF-TrkB signaling is closely related to Gad1 expression in depression and anxiety, and regulates GABAergic mechanisms by inducing Gad1 expression." (PMID 28872625, 2017). "This relationship was moderated by self-efficacy and BDNF genotype, such that when individuals appraised high self-efficacy, those with the Val/Val genotype, compared to Met carriers, reported greater depression scores when they perceived feeling lonely." (PMID 28769852, 2017).